SMAD2 (SMAD family member 2)
Diseases named in the same sentence as SMAD2 in open-access papers (continued):
Sharing a sentence is not in itself a finding about the gene and the disease.
renal fibrosis (continued). "Furthermore, best docking binding energy −6.6 kcal/mol was determined between SMAD2 and gastrodin.Thus, this molecular docking results suggest that gastrodin might be one of the potential inhibitor molecule for renal fibrosis." (PMID 36733505, 2023). "Therefore, whether folate deficiency might enhance renal fibrosis via activation of STAT3 and Smad2/3 signaling is worthy of investigation." (PMID 37630806, 2023). "Interestingly, we could not detect this hallmark change in the expression of proteins involved in renal fibrosis, such as E-cadherin, α-SMA, and Smad2/3." (PMID 35457146, 2022). "The activation of Smad2 and Smad3 results in aggressive ECM deposition in interstitial and glomerulus that cause interstitial fibrosis and glomerulosclerosis in kidney respectively, while the inhibition of Smad3 phosphorylation retarded renal fibrosis in UUO rats." (PMID 32957963, 2020). "Studies have shown that SMAD2 and SMAD3 are widely activated in renal fibrosis of CKD patients and animal models." (PMID 40514734, 2025). "TGF-β1 mediates fibrotic and inflammatory responses through the Smad signaling pathway, with Smad2/3 being a key molecule involved in TGF-β1 activity, leading to renal fibrosis." (PMID 40284165, 2025). "Mice and human primary renal interstitial cells treated with miR-1908 decreased renal fibrosis via the suppressed protein expression of TGF-β1, Smad2/3 and MMP-2." (PMID 40141345, 2025). "And, knockout of ISG15 led to decreased TGFβR1 and its downstream p-Smad2 levels, reduces transcription levels of fibrotic genes such as α-SMA, Fn1, and Vimentin, ultimately inhibited renal fibrosis." (PMID 39113797, 2024). "A recent investigation demonstrated that a Klotho-derived peptide 1 in combating renal fibrosis by binding to TβR2, thereby disrupting the interaction between TGF-β and TβR2, suppressing fibroblast activation, and thwarting TGF-β-induced Smad2/3 activation." (PMID 39325739, 2024). "We stimulated macrophages, polarized them in a high-glucose environment, and cocultured them with mesangial cells for 48 h to simulate the fibrotic niche in vitro to clarify the synergistic effect of Smad2/3 and YAP in promoting renal fibrosis." (PMID 38890734, 2024). "The protective effects of olmesartan on E protein-induced renal fibrosis were evaluated by renal-function assessment, pathologic alterations, inflammation, and the TGF-β1/Smad2/3 signaling pathway." (PMID 37256223, 2023). "Overall, these data suggested that SMAD2 and SMAD3 are important targets of SIRT2 against renal fibrosis." (PMID 37777567, 2023). "Released HMGB1 can ultimately lead to renal fibrosis by triggering inflammation and activating TGF-β1/Smad2/3 signaling." (PMID 37256223, 2023). "Next, in order to explore mechanisms by which CHRFAM7A expression can alleviate UUO‐induced renal fibrosis, we determined mRNA and protein expression of TGF‐β1 and Smad2/3 in kidneys from each group." (PMID 36479618, 2023). "In the process of renal fibrosis in an animal model with DKD, the increased level of TGF-β interacts with its receptors and triggers activation of Smad-dependent pathways, Smad2 and Smad3 presented higher expression in kidney tissues, and Smad7 was inhibited." (PMID 36601125, 2022). "Focusing on the role of TGF-β1 expression in renal fibrosis, it was proved that UCG downregulated the protein expressions of TGF-β1, TGF-β receptor I, receptor II and Smad2/3, and upregulated the protein expressions of SnoN and Smad7." (PMID 35924053, 2022). "It cannot be proved that TGF-β1/Smad2/3 signaling pathway is the only mechanism of JP to inhibit EMT and improve renal fibrosis." (PMID 35591863, 2022). "We also evaluated changes in the expressions of Smad2, Smad3, and TGF-β1, which are considered valuable signaling molecules in the progression of renal fibrosis." (PMID 35646947, 2022). "Accumulating evidence indicates the critical function of Smad2/3 and AKT signaling in renal fibrosis progression." (PMID 35485286, 2022).
renal fibrosis (continued). "A disintegrin and metalloproteinases (ADAMs) are involved in renal fibrosis and TGF‐β/Smad2/3 signaling upregulates Adam 10, 12, 17, 19 expression in renal cells and in unilateral ureteral obstruction models of renal fibrosis." (PMID 33529442, 2021). "NLRP3 also has inflammasome-independent effects in tubular epithelial cells, including participating in SMAD2 and SMAD3 phosphorylation in response to TGFβ signaling, triggering renal fibrosis." (PMID 32521623, 2020). "During the early stages of renal fibrosis, continuous inflammatory response of renal tubular cells and immune cells promotes TGF‐β/Smad pathway activation and overexpressed Smad2 and Smad3 further activate the NF‐kB pathway in turn." (PMID 32253812, 2020). "Smad2 and Smad3, two major downstream mediators of transforming growth factor-β1 (TGF-β1), play a dominant role in kidney dysfunction and renal fibrosis." (PMID 32957963, 2020). "We next assessed mRNA expression of epithelial mesenchymal transition-(EMT)-related molecules, since phosphorylated Smad2/3 complex translocates to nucleus and then increases transcription of EMT-related molecules to progress renal fibrosis." (PMID 32047249, 2020). "In addition, miR-101a could target and downregulate KDM3A expression, which led to elevated TGIF1, inhibited expression of Collagen I (Col1a1), fibronectin, α-SMA, YAP1, and TGF-β2 along with the extent of Smad2/3 phosphorylation, as well as delayed renal fibrosis degree." (PMID 32092824, 2020). "In this study, we examined two critical downstream markers of TGF-β pathway—SMAD2 and SMAD4—involved in the progression of renal fibrosis in DN." (PMID 31390845, 2019). "The current study showed that exercise training suppressed TGF-β, p-Smad2/3, CTGF, MMP2, and MMP9 expression to decrease renal fibrosis." (PMID 29461477, 2018). "Among the Smad molecules, Smad2 and Smad 3 play roles as key regulators for TGF-β1/Smad signaling, and they are strongly activated in renal fibrosis in DN." (PMID 26974954, 2016). "Although the TGF-β signaling pathway is mediated by Smad2 and Smad3, Smad2 protects against TGF-beta/Smad3-mediated renal fibrosis." (PMID 28100935, 2016). "PTX has also been shown to inhibit renal fibrosis in a rat model of crescentic glomerulonephritis by affecting renal tubular EMT through blockade of TGF-β1 expression and Smad2/3 activation." (PMID 23028611, 2012). "Overall, the results indicate that spinach extract can mitigate the activation of the TGF-β1/SMAD2/αSMA and CTGF pathways, thus reducing renal fibrosis and preventing the development of diabetic kidney disease by inhibiting epithelial- and endothelial-to-mesenchymal transition." (PMID 40429870, 2025). "­suggested that the effect of LCZ696 to alleviate cyclophosphamide-induced renal fibrosis was obviously superior to that of valsartan, and the protective effect may owe to the ability to downregulate TGF-β/Smad2,3/PAI-1 and NF-κB signaling." (PMID 39165231, 2024). "Moreover, the administration of EPE to db/db mice increased the expression levels of p- PKCα/t-PKCα but decreased the expression levels of VEGF and renal fibrosis biomarkers (TGF-β1, collagen IV, p-Smad2, p-Smad3, and Smad4), as shown by Western blot analyses." (PMID 38928391, 2024). "Therefore, our study demonstrated that RSGB suppressed the inflammatory response and cell cycle by inhibiting the Tgfβ1/Smad2/3 pathway, Wnt4/β-Catenin pathway and NGFR/NF-κB pathway, thereby exerting an anti-renal fibrosis effect." (PMID 37198665, 2023). "In UUO model group, Tgfβ1/Smad2/3 pathway, Wnt4/β-Catenin pathway, and NGFR/NF-κB pathway were activated, which led to inflammatory response and accelerated cell proliferation, thus promoting the progression of renal fibrosis." (PMID 37198665, 2023). "However, TGF-β1 is a key inducer of renal fibrosis, and renal inflammation and oxidative stress are the influencing factors for inducing TGF-β1/Smad2/3 signaling pathway." (PMID 36733505, 2023).
renal fibrosis (continued). "In our present study, normalization of TGF-β1, p-Smad2/3, p-P38, p-ERK1/2 and p-JNK in Nimbidiol-treated diabetic mice suggested that Nimbidiol may mitigate renal fibrosis in type-1 DN by attenuating TGF-β1/Smad and MAPK signaling pathways." (PMID 36522378, 2022). "Regarding the mechanism of RRR against renal fibrosis, some studies have shown that its nephroprotective effect was to reduce the expressions of TGF-β1, TGF-β receptor I (TGF-β RI), TGF-β RII, Smad2, p-Smad2, Smad3, p-Smad3, and Smad4, meanwhile increasing Smad7 (Zhang ZH." (PMID 35924053, 2022). "However, the transcription factor Smad2 signaling mediates endothelial-related ECM deposition and renal fibrosis." (PMID 35865947, 2022). "An epithelial-to-mesenchymal transition (EMT) is involved in renal fibrosis, and an experiment discovered OTA activated TGF-β/Smad2/3 and B-catenin/Wnt signaling pathways to induce EMT and renal fibrosis by evidence of increasing expression of α-SMA and fibronectin." (PMID 34681895, 2021). "Moreover, lncRNA MEG8 downregulates the expression of Smad2, Smad3, Colla1 and α-SMA, and leads to the formation of myofibroblasts, which ultimately alleviates the progression of renal fibrosis." (PMID 34477472, 2021). "Interestingly, in contrast to the anti-fibrogenic role of Smad2 in UUO mouse kidney, conditional deletion of Smad2 from fibroblasts driven by the Fibroblast-specific Protein 1 (Fsp1) promoter reduces renal fibrosis in STZ-induced DN." (PMID 34360646, 2021). "In addition, TGF-β1 downstream Smad2/3-independent signaling pathways, including MAPKs, PI3K/Akt, RhoA, and Wnt/β-catenin, contribute to renal fibrosis." (PMID 32455132, 2020). "The data showed that miR-294/miR-133 mimics could potently inhibit the phosphorylation of SMAD2/3 and ERK1/2 to inhibit TGF-β1-induced EMT in HK2 cells, further restoring renal fibrosis." (PMID 32641100, 2020). "AS-IV appears to delay TGF-β1-, Smad2-/3-, and α-SMA-induced renal fibrosis in diabetic mice." (PMID 32515466, 2020). "We found rhubarb extracts suppressed TGF-β/Smad3-mediated renal fibrosis by reducing the TGF-β1, transforming growth factor-β receptor I (TGF-β RI), transforming growth factor-β receptor II (TGF-β RII), Smad2, p-Smad2, Smad3, p-Smad3, and Smad4, meanwhile increased Smad7." (PMID 30271345, 2018). "TGF-β1, a central mediator in renal fibrosis, through Smad3, but not Smad2, to exert its fibrotic activities on GMCs." (PMID 27010029, 2016). "And we observed that MMF could inhibit renal fibrosis in an experimental animal CAN model by down-regulating the expression of TGF-β1 and Smad2 in grafts." (PMID 22747784, 2012). "Similarly, in the case of renal fibrosis, HQD could ameliorate the ipsilateral kidney fibrosis in a dose-dependent manner by downregulation of TGF-β1, TGF-β receptor I and II, Smad2, P-Smad2, Smad4, α-SMA, and collagen I, III, and IV expression." (PMID 39519465, 2024). "Thus, TGF-β1 is considered as a potential biomarker for renal fibrosis and inhibiting TGF-β1/Smad2/3 pathway may represent an effective therapy for DN associated with progressive real fibrosis." (PMID 38357745, 2024).
renal fibrosis (continued). "MC stabilizers such as SCG may alleviate hyperuricemia-induced renal fibrosis by inhibiting the recruitment of MCs and suppressing the TGF-β1/Smad2/3 pathway, and attenuate mitochondrial structural damage and relieve renal oxidative stress by inhibiting the production of Ang II." (PMID 37446016, 2023). "Importantly, deficiency of SMAD2 and SMAD3 improved the renal fibrosis in UUO mice, and there is no obviously difference in renal fibrosis between WT and Sirt2tKO mice when SMAD2 and SMAD3 is deficient." (PMID 37777567, 2023). "C. sinensis could exert anti-fibrotic activity by mediating TGF-β1/Smad signaling pathway, and attenuate renal fibrosis in 5/6 nephrectomy rats by abrogating the expression of TGF-β1, Smad2/3, TβRI, TβRII, p-Smad2/3, α-SMA, and FSP1, and upregulated Smad7 to inhibit EMT." (PMID 35645822, 2022). "Studies have indicated that TGF-β1 can activate Smad2 and Smad3, which then activate myofibroblasts, leading to excessive production of extracellular matrix (ECM) and inhibition of ECM degradation, thereby inducing renal fibrosis and ultimately chronic renal failure." (PMID 35734171, 2022). "Moreover, YAP/TAZ are mechanoregulators that bind to Smad transcription factors, the central mediators of TGF-β elicited profibrotic responses in fibroblasts, suggesting that TGF-β may induce renal fibrosis in a YAP/TAZ- and Smad2/3-dependent manner." (PMID 33445676, 2021). "However, unlike the diverse role of Smad2 and Smad3 in renal fibrosis, blocking Smad2 or Smad3 is capable to attenuate AKI." (PMID 31754396, 2019). "Similarly to Smad2, also Smad7, a member of inhibitory group of I-Smads, is a negative regulator of TGF-β1/Smad3 signaling, and a growing number of papers indicate its protective role in renal fibrosis." (PMID 27610006, 2016). "In addition, SMAD2 and SMAD3 knockout augmented the production of inflammatory factor (TNFα and IL-6), while SIRT2-mediated NLRP3 deacetylation protects against inflammation, indicating SIRT2 may be a more attractive target to improving renal fibrosis." (PMID 37777567, 2023). "Thus, targeting CCL20 by miR-143-5p could alleviate renal fibrosis progression by regulating fibroblast proliferation and ECM deposition via the Smad2/3 and AKT signaling, providing a potential therapeutic target for environmental lead contamination-evoked fibrotic kidney disease." (PMID 35485286, 2022). "Furthermore, according to a recent study in kidney fibrosis, the use of a YAP inhibitor ameliorates renal fibrosis both in vitro and in vivo by decreasing the cellular levels of Smad2 and 3, thus the active YAP/TAZ complex cooperates with TGF-β to induce fibrosis in a Smad2/3-dependent manner." (PMID 33409282, 2020). "In addition, overexpression of latent TGFβ1 was shown to decrease both SMAD2/3 activation (transcription factors of canonical TGFβ1 signaling) and the number of myofibroblasts, which is in line with findings that SMAD3 knockout mice are protected from renal fibrosis." (PMID 29651290, 2018). "In this study, we demonstrate that PR-619 suppresses renal fibrosis and reduces Smad4 expression but not the expression of TGF-β receptors, Smad2, or Smad3, in mice with unilateral ureteral obstruction (UUO), a well-established mouse model of renal fibrosis." (PMID 30114247, 2018). "We recently demonstrated that Smad3, but not Smad2, is the key transcription factor responsible for TGF-β-mediated renal fibrosis." (PMID 23301086, 2013). "Indeed, as a therapeutic approach to reversing fibrosis, interference with SMAD2 acetylation either by the DAXX transcription factor, as shown in hepatocytes, or by the p300/CBP inhibitor garcinol, as shown in a nondiabetic renal fibrosis model, can be considered." (PMID 34576109, 2021).
pulmonary fibrosis (163 papers, 2006 to 2026). Chronic progressive interstitial lung disorder characterized by the replacement of the lung tissue by connective tissue, leading to progressive dyspnea, respiratory failure, or right heart failure. "The NP-mediated amelioration of pulmonary fibrosis was associated with suppression of TGF-β1/SMAD2 and IL-11/ERK signaling pathways as evidenced by Western blotting analysis." (PMID 35731866, 2022). "VD deficiency aggravates bleomycin‐induced pulmonary fibrosis through activating TGF‐β/Smad2 signaling." (PMID 35906886, 2022). "These pathways were disease-relevant because the levels of TGF-β and Ang II were increased and positively correlated with Smad2/3 in tissues from patients with idiopathic pulmonary fibrosis or scleroderma-associated interstitial lung disease." (PMID 35685407, 2022). "The pulmonary fibrosis injury of broilers in the model group in our study was consistent with the finding that activation of the TGF-β1/Smad2-dependent pathway causes pulmonary fibrosis, as reported by Maxwell." (PMID 36611616, 2022). "Cadmium exposure has recently been implicated as potential exogenous risk factor for pulmonary fibrosis via its activation of SMAD2/3/4-dependent signaling in the murine lung." (PMID 33859634, 2021). "The downregulation of miR-486-5p is found in lung tissues of IPF patients, and its overexpression in mouse models reduces lung fibrosis through targeting SMAD2, a crucial mediator of pulmonary fibrosis and implicated in TGF-β1 signaling." (PMID 34819948, 2021). "The mechanism through which vitamin D deficiency aggravates TGF-β/Smad2/3-mediated EMT during BLM-induced pulmonary fibrosis remains obscure." (PMID 31775746, 2019). "Vitamin D deficiency exacerbates BLM-induced pulmonary fibrosis partially through aggravating TGF-β/Smad2/3-mediated EMT in the lungs." (PMID 31775746, 2019). "Data above provide evidence that vitamin D deficiency exacerbates BLM-induced pulmonary fibrosis partially through aggravating TGF-β/Smad2/3-mediated EMT in the lungs." (PMID 31775746, 2019). "Neutrophil-elastase-deficient mice are resistant to asbestos- and bleomycin-induced pulmonary fibrosis, which are associated with reduced Smad2/3 phosphorylation." (PMID 31772282, 2019). "Mechanistically, vitamin D deficiency exacerbated pulmonary fibrosis partially through aggravating BLM-induced TGF-β/Smad2/3-mediated EMT in the lungs." (PMID 31775746, 2019). "In addition, they demonstrated that OGG1 deficiency relieved pulmonary fibrosis and decreased the expression of Smad7 and phosphorylation of SMAD2/3 in bleomycin‐treated mice." (PMID 36788635, 2023). "In the present study, we investigated whether vitamin D deficiency aggravates Smad2/3-mediated EMT in BLM-induced lung fibrosis." (PMID 31775746, 2019). "TRIM47 targets PPM1A for ubiquitination, leading to its degradation via the 26S proteasome complex, which in turn increases the phosphorylation of Smad2/3 and contributes to lung fibrosis." (PMID 40901482, 2025). "In respiratory system research, bleomycin-induced mouse models of pulmonary fibrosis were used to demonstrate that ATF4-induced lncRNA lnc949 alleviates fibrosis by modulating TGF-β/Smad2/3 signaling." (PMID 40777108, 2025). "In summary, GSR deficiency exacerbates and promotes pulmonary fibrosis by inhibiting GSH levels and increasing the accumulation of ROS, thereby activating the TGF-β/Smad2 signaling pathway, suggesting GSR is a potential therapeutic target for IPF." (PMID 40723921, 2025). "In conclusion, our findings demonstrate that GSR deficiency aggravates pulmonary fibrosis by impairing antioxidant defense mechanisms, promoting EMT, and activating fibroblasts through the TGF-β/Smad2 signaling." (PMID 40723921, 2025). "Inhibiting TRIM47 expression can suppress the expression of Vimentin, α-SMA, and CTGF protein, reduce Smad2/3 phosphorylation and hydroxyproline production, thereby mitigating pulmonary fibrosis." (PMID 40901482, 2025).